RUNX1 (RUNX family transcription factor 1)
Diseases named in the same sentence as RUNX1 in open-access papers (continued):
Sharing a sentence is not in itself a finding about the gene and the disease.
acute myeloid leukemia (continued). "RUNX1 is also known as AML1, for it is frequently involved in acute myeloid leukemia‐causing translocations." (PMID 33085215, 2021). "Mutations of the haematopoietic master regulator RUNX1 are associated with acute myeloid leukaemia, familial platelet disorder and other haematological malignancies whose phenotypes and prognoses depend upon the class of the RUNX1 mutation." (PMID 33397648, 2021). "Mutations and translocations in RUNX1 are well established as causes of myelodysplastic syndrome or acute myelogenous leukemia." (PMID 32498288, 2020). "Among patients with U2AF1 gene mutations, those with ASXL1 mutations were prone to develop into acute myeloid leukemia, those with RUNX1 mutations had an increased risk of relapse, and those with TET2 mutations had higher 1-year survival rate." (PMID 33122737, 2020). "RUNX1 gene mutations are frequently found in acute myeloid leukemia (AML) with a particularly poor prognosis." (PMID 31048839, 2019). "Somatic and germline mutations of RUNX1 cause ~10% of acute myeloid leukemia (AML) as well as preleukemic diseases with predisposition to AML, such as myelodysplastic syndrome (MDS) (~10%)." (PMID 31048839, 2019). "Gain and loss of function in RUNX1 has been correlated with cancer progression and metastasis, most notably in acute myeloid leukemia." (PMID 31635436, 2019). "For example, inactivating RUNX1 mutations frequently occur in acute myeloid leukemia, where upregulation of RUNX2 or RUNX3 exhibits anti-leukemic effects." (PMID 30216339, 2018). "Generation of fusion proteins such as RUNX1/ETO and RUNX1/Evi1 through leukemic associated-chromosomal translocation are frequently observed in acute myeloid leukemia (AML)." (PMID 29047338, 2017). "For instance, Patient 4, a 19-year-old male with a history of longstanding unexplained thrombocytopenia and learning disability, developed acute myeloid leukemia and was suspected to carry a pathogenic variant in RUNX1,ETV6 or ANKRD26." (PMID 28104920, 2017). "Inherited mutations in RUNX1 cause familial platelet disorder with predisposition to acute myeloid leukemia (FPD/AML)." (PMID 29326930, 2017). "Alteration in RUNX1 due to chromosomal translocations and mutations are causally connected to the onset of acute myeloid leukemia in humans." (PMID 26990877, 2016). "In human acute myeloid leukemia cases, the enhancer lacks point mutations but binds the RUNX1-ETO oncoprotein." (PMID 25938608, 2015). "Cytogenetically normal acute myeloid leukemia (CN-AML) patients harboring RUNX1 mutations have a dismal prognosis with anthracycline/cytarabine-based chemotherapy." (PMID 26177509, 2015). "Among the genes included in the signature there is RUNX1, which encodes for a transcription factor that is pivotal in the development of haematopoietic cells and that can be involved in acute myeloid leukaemia, whose frequency is high among DSP." (PMID 25701644, 2015). "Of note, germline mutations ofRUNX1 that result in haploinsufficiency of RUNX1 can lead to anautosomal dominant disorder referred to as familial platelet disorder with a propensityto acute myeloid leukemia (FPD/AML)." (PMID 25415051, 2014). "RUNX1 is a classic tumor suppressor gene in acute myeloid leukemia (AML) and loss of RUNX1 causes hyperproliferation and abnormal morphogenesis in a 3D model of breast epithelial cells." (PMID 23077491, 2012). "The extract of COSMIC shows that there are 90 RUNX1 mutations in 688 patients with acute myeloid leukemia." (PMID 22720055, 2012). "JMJD1C, a histone demethylase, facilitates the preservation of leukaemic stem cells via epigenetic regulation, whereas RUNX1, a principal regulator of haematopoiesis, often displays mutations or dysregulation in acute myeloid leukaemia that hinder differentiation and lineage fidelity." (PMID 41492215, 2026).
acute myeloid leukemia (continued). "In our previous studies, we demonstrated that isoflavonoid 8-hydroxydaidzein induced apoptosis by downregulating acute myeloid leukemia (AML)-associated genes such as RUNX1, CCND2, and MYC in U937 cells while upregulating CDKN1A (p21) and suppressing BCL2 expression in K562 cells." (PMID 40508126, 2025). "To evaluate the impact of the leukemic fusion genes on the course of an adenoviral infection, we created stable B cell lines expressing either the RUNX1 fusion gene commonly associate with ALL (ETV6/RUNX1), or the RUNX1 fusion gene commonly associated with acute myeloid leukemia (RUNX1/MTG8)." (PMID 41497616, 2025). "The RUNX1 gene, located on chromosomal band 21q22, plays a critical role in the formation of the hematopoietic system, and mutations in this gene are associated with various hematological malignancies, including acute myeloid leukemia (AML)." (PMID 40558237, 2025). "Additionally, germline mutations in RUNX1 contribute to familial platelet disorder with a predisposition to acute myeloid leukemia (FPD/AML) occurrence." (PMID 36766699, 2023). "Somatic mutations of RUNX1 are frequently found and have been intensively studied in hematological malignancies, such as acute myeloid leukemia (AML), acute lymphoblastic leukemia (ALL), myelodysplastic syndromes (MDS), and chronic myelomonocytic leukemia (CMML)." (PMID 35562964, 2022). "Mutations of RUNX1 were occurred in nearly 10% acute myeloid leukemia (AML) patients." (PMID 34088969, 2021). "Moreover, RUNX1 is one of the most frequently mutated genes in a variety of hematological malignancies, such as acute myeloid leukemia and familial platelet disorder." (PMID 33434583, 2021). "RUNX1 intragenic deletions as well as point mutations have been described as the cause of familial platelet disorders with propensity to acute myeloid leukemia, suggesting that loss of RUNX1 function could be involved in myeloid transformation." (PMID 34203905, 2021). "•A RUNX1/RUNX1T1-associated gene expression network drives acute myeloid leukemia." (PMID 33217477, 2021). "Genetic disruptions to the RUNX1 gene are frequently associated with acute myeloid leukaemia." (PMID 34440349, 2021). "Somatic translocations and mutations of RUNX1 are causative of haematological diseases such as myelodysplastic syndrome, acute myeloid leukaemia, acute lymphoblastic leukaemia, chronic myelomonocytic leukaemia and acute megakaryoblastic leukaemia with familial platelet disorder." (PMID 32323916, 2020). "This leads to impaired bone marrow differentiation and may contribute to the leukemic transformation in cases of acute myeloid leukemia associated with the decreased RUNX1 activity." (PMID 33170359, 2020). "Acquired genetic alterations in RUNX1 are frequently associated with numerous myeloid malignancies, especially acute myeloid leukaemia (AML) (40% of FAB M0 immature AMLs 1) and more rarely with T cell acute lymphoblastic leukaemia (T‐ALL) (25% of early thymic immature T‐ALL (ETP‐ALL) 2)." (PMID 27997762, 2017). "In addition, loss of RUNX1 increases RUNX2 mRNA level in acute myeloid leukemia cells, and depletion of RUNX2 increases RUNX1 mRNA expression in SaoS-2 and MDA-231 cells." (PMID 29050333, 2017). "We describe the largest series of acute myeloid leukemia (AML) cases demonstrating varying degrees of B-cell antigen expression associated with various RUNX1 lesions other than fusion with RUNX1T1." (PMID 40282530, 2025). "For patients with a history of or a new diagnosis of acute myeloid leukemia (AML) at the time of ordering (n = 52), the most commonly mutated genes were RUNX1, SRSF2, and IDH2 (each with 16 variants)." (PMID 39691272, 2024). "Germline mutations in the runt-related transcription factor 1 gene (RUNX1) were first described in 1999, as causing inherited thrombocytopenia with a propensity to develop acute myeloid leukemia (AML)." (PMID 40225162, 2023).
acute myeloid leukemia (continued). "Acute myeloid leukemia (AML) with mutated RUNX1 (RUNX1mut) is considered to have an unfavorable prognosis." (PMID 36358658, 2022). "Acute myeloid leukemia with runt-related transcription factor 1 gene mutation (RUNX1+ AML) is associated with inferior response rates and outcome after conventional chemotherapy." (PMID 34059800, 2021). "H3K27M and K27I mutations have been identified in adult Acute Myeloid Leukemia (AML), where they associate with and collaborate with RUNX1 mutations and translocations, to promote transformation." (PMID 31086012, 2019). "A number of haematopoietic malignancies are caused by mutations in RUNX1, in particular in acute myeloid leukemia (AML)." (PMID 29991720, 2018). "Alterations of RUNX1 in acute myeloid leukemia (AML) are associated with either a more favorable outcome in the case of the RUNX1/RUNX1T1 fusion or unfavorable prognosis in the case of point mutations." (PMID 30050054, 2018). "This megakaryocyte maturation block is reminiscent of Familial Platelet Disorder with Predisposition to Acute Myeloid Leukemia (FPD/AML), almost exclusively the result of germline heterozygous RUNX1 gene mutations/deletions." (PMID 29300724, 2018). "RUNX1 mutation in breast cancer can predict poor outcome, all indicating that defective RUNX1 function might also act as an important factor in epithelial tumors, not only in acute myeloid leukemia." (PMID 29245924, 2017). "Human RUNX1 gene is one of the most frequent target for chromosomal translocations associated with acute myeloid leukemia (AML) and acute lymphoid leukemia (ALL)." (PMID 24655352, 2014). "RUNX1/ETO, which causes acute myeloid leukemia (AML), acts as a dominant-negative repressor of RUNX1 target genes, including colony-stimulating factor 1 receptor (CSF1R/c-fms), GM-CSF, tumor suppressor p14(ARF) and the retinoic acid receptor β (RARB)." (PMID 23860209, 2013). "Another bioinformatics analysis related to leukemia indicated that HTR1F could have a crucial role in RUNX1 mutation acute myeloid leukemia (AML)." (PMID 41007799, 2025). "This case is reported due to its novelty in demonstrating the efficacy of avapritinib, a selective KIT inhibitor, in a rare systemic mastocytosis-associated acute myeloid leukemia (SM-AML) patient with non-D816V KIT mutations and RUNX1::RUNX1T1 fusion." (PMID 41473436, 2025). "In this study, we performed an integrated analysis of bulk and single-cell DNA sequencing data of core-binding factor acute myeloid leukemia patients, defined by the presence of a RUNX1::RUNX1T1 or CBFB::MYH11 fusion gene." (PMID 41152985, 2025). "The RUNX1 gene, located on chromosome 21, was first identified in 1991 and named the acute myeloid leukemia gene due to its involvement in the translocations in patients with acute myeloid leukemia." (PMID 40356603, 2025). "We recently reported a de novo acute myeloid leukemia (AML) patient harboring both BCR::ABL1 p190 isoform and RUNX1::MECOM fusion, a rare and high-risk molecular profile." (PMID 41245943, 2025). "These genes belonged to the Reactome signatures for “membrane trafficking”, “metabolism of RNA” and “transcriptional regulation by RUNX1”, pathways involved in the proliferation of glioblastoma and acute myeloid leukemia cells." (PMID 38684783, 2024). "Specifically, somatic RUNX1 mutations are most commonly found in myelodysplastic syndrome (MDS) and acute myeloid leukemia (AML)." (PMID 37581927, 2023). "Previous studies have shown that in acute myeloid leukemia with RUNX1 mutations, DACH1 mRNA expression is upregulated after RUNX1 mutations occur." (PMID 37766305, 2023).
acute myeloid leukemia (continued). "The researchers documented mutations of the RUNX1 gene in acute myeloid leukaemia (AML), acute lymphoid leukaemia (ALL), and familial platelet disorder with a predisposition to acute myeloid leukaemia (FPD/AML)." (PMID 37759525, 2023). "There are two studies that provide evidence for cross-talk between CARM1 and RUNX1 (also called acute myeloid leukemia [AML] 1), a transcription factor that regulates genes with important functions in normal and malignant hematopoiesis." (PMID 37536629, 2023). "Furthermore, RUNX1 somatic mutations and chromosomal rearrangements are frequently observed in hematological malignancies such as acute myeloid leukemia (AML), ALL, and chronic myelomonocytic leukemia." (PMID 37444447, 2023). "The differential diagnosis includes other malignancies with cutaneous manifestations, such as CD56+ acute myeloid leukemia (AML), RUNX1-mutated AML, Nasal-type extranodal NK/T cell lymphoma, Subcutaneous panniculitis-like T cell lymphoma (SPTCL) and Cutaneous T cell lymphoma." (PMID 38132278, 2023). "In this study, in the II genotype sequence, we detected a Runx1 transcription-factor binding site, which was first discovered in acute myeloid leukemia." (PMID 36899708, 2023). "A key feature of such therapy-induced acute myeloid leukemia (t-AML) is recurrent chromosomal translocations involving AML1 (RUNX1) or MLL (KMT2A) genes." (PMID 36077220, 2022). "Inactivation by the mutation or deletion of ETV6, RUNX1, and GATA3 has also been described in patients with Acute Myeloid Leukemia (AML) and correlates with poor outcomes in ETP-ALL." (PMID 35626079, 2022). "Acute myeloid leukemia (AML) often occurs due to chromosomal abnormalities or mutations in the genes NPM1, CEPBA, RUNX1 and FLT3 and is characterized by an over-accumulation of abnormal cells called myeloblasts." (PMID 35159109, 2022). "In acute myeloid leukemia (AML), RIPK3 signaling might be epigenetically repressed in leukemic cells isolated from a subgroup of AML patients such as AML with RUNX1-ETO or FLT3-ITD mutations." (PMID 35561683, 2022). "For example, KLF6 is highly expressed in acute myeloid leukaemia and can be regulated by the pro-oncogenic fusion protein RUNX1-ETO to promote the progression of acute myeloid leukaemia." (PMID 36615000, 2022). "This sequence is homologous to three highly conserved transcription factor-binding sites for FREAC-4, SOX17, and acute myelogenous leukemia-1 (AML-1) (also called RUNX1 or CBFα)." (PMID 36420268, 2022). "Runx1 is recognized as the gene responsible for the development of acute myeloid leukemia, and Runx1 knockout mice are embryonically lethal due to the complete absence of hematopoiesis in the fetus." (PMID 35270012, 2022). "Acute myeloid leukemia (AML) with ≥2% plasmacytoid dendritic cells (pDC) has been recently described as AML with pDC differentiation (pDC-AML) characterized by pDC expansion with frequent RUNX1 mutations." (PMID 35884435, 2022). "The orthologue of Lz in mammals is RUNX1, with broad hematopoietic function at many developmental stages, and RUNX1 is often dysregulated in acute myeloid leukemias." (PMID 34713801, 2021). "The fusion oncogene RUNX1/RUNX1T1 encodes an aberrant transcription factor, which plays a key role in the initiation and maintenance of acute myeloid leukemia." (PMID 33483506, 2021). "RUNX1 partner transcriptional co-repressor 1 (RUNX1T1) earned prestige for its fusion with Runt-related transcription factor 1 (RUNX1) in acute myeloid leukemia." (PMID 34540896, 2021). "Cyclin D2 has critical roles in B cell activation and also has been shown to be positively regulated by the RUNX1-ETO fusion oncoprotein in acute myeloid leukemia." (PMID 34810221, 2021). "The fusion protein ETV6-RUNX1 sustains BCP-ALL, RUNX1-ETO is highly frequent in acute myeloid leukemia, RUNX1-MECOM leads to myelodysplasia and acute myeloid leukemia CBFA2T3-GLIS2, and RUNX1-CBFA2T3 is found in acute megakaryoblastic leukemia." (PMID 33743795, 2021).
acute myeloid leukemia (continued). "The pro-oncogenic fusion protein RUNX1-ETO upregulated the expression of KLF6 in acute myeloid leukaemia." (PMID 32998281, 2020). "In summary, we reported 1 case of acute myeloid leukemia with the NUP98/RARG fusion gene and the RUNX1 mutation that resembled acute promyelocytic leukemia in regards to its morphologic and immunologic features." (PMID 33019444, 2020). "Chromosomal rearrangements activate the expression of RUNX1 by perturbing its transcriptional control to contribute to acute myeloid leukemia pathogenesis." (PMID 32746865, 2020). "RUNX1-ETO is found in 10–15% of acute myeloid leukemia and interferes with the expression of genes that are essential for myeloid differentiation." (PMID 31826021, 2019). "RUNX1 is frequently translocated in acute-myeloid leukaemia and has previously been shown to be exquisitely susceptible to DSBs." (PMID 31127293, 2019). "Promoter-Capture Hi-C assays, gene expression, and transcription-factor binding data are used to construct a RUNX1-ETO-dependent dynamic gene regulatory network that maintains acute myeloid leukemia (AML)." (PMID 31533028, 2019). "Genes associated with the pathogenesis of acute myeloid leukemia, such as DNMT3A, NRAS, RUNX1, EZH2, and KRAS, were more commonly mutated in the hypermethylation group." (PMID 30635552, 2019). "Mutations of RUNX1 cause ~10% of acute myeloid leukemia (AML) with a particularly poor prognosis." (PMID 31048839, 2019). "Chromosomal translocations and inversions that target the transcription factors RUNX1 and CBFβ constitute the group of core-binding factor acute myeloid leukemias, CBF-AMLs." (PMID 30654457, 2019). "CBFA2T2 has been known as a fusion partner of RUNX1 in acute myeloid leukemia, suggesting a role of CBFA2T2 in cancer development." (PMID 29162985, 2017). "In acute myeloid leukemias, diverse chromosomal breakage and fusion events result in truncation of the RUNX1 gene product and deletion or replacement of the C‐terminal transactivation domain with heterologous sequences." (PMID 27869314, 2017). "VEGF is reported to be repressed by RUNX1 in acute myeloid leukemia, whereas PF4 (platelet factor 4) is upregulated by RUNX1 in human erythroleukemia cells." (PMID 29050333, 2017). "It was well known that RUNX1 was first identified in acute myeloid leukemia and played important roles in regulating the functions of hematopoietic cells." (PMID 26716895, 2016). "Although impaired RUNX1 activity is frequently important for establishing a pre-leukemic stage, WT RUNX1 protein is nonetheless necessary for maintaining AML1-ETO Acute Myeloid Leukemia (AML)." (PMID 26808730, 2016). "RUNX1 was originally recognized to display tumor-suppressive ability due to its role in acute myeloid leukemia tumorigenesis." (PMID 26984280, 2016). "Acute myeloid leukaemia often originates from a chromosomal translocation creating a RUNX1/ETO fusion protein." (PMID 26018585, 2015). "RUNX1 loss will produce a RUNX1-ETS fusion protein, identified as acute myeloid leukemia (AML)." (PMID 38817386, 2024). "In acute myeloid leukemia, RUNX1 was shown to be involved in IL-8 regulation." (PMID 39050851, 2024). "For hematological malignancies, hereditary predisposition was first identified in chronic lymphocytic leukemia (CLL) and acute myeloid leukemia (AML), which has led to the identification of several germline mutations, such as RUNX1, CEBPA, GATA2, ANKRD26, DDX41 and ETV6 mutations." (PMID 36998465, 2023). "Previous studies have found germline RUNX1 variants in 3% of patients with acute myeloid leukemia; however, the frequency of germline RUNX1 variants in less advanced myeloid neoplasms has not been examined." (PMID 40225162, 2023).